HIF1A (hypoxia inducible factor 1 subunit alpha)
Diseases named in the same sentence as HIF1A in open-access papers (continued):
Sharing a sentence is not in itself a finding about the gene and the disease.
cancer (continued). "The transcriptional factor HIF-1α regulates various genes in the hypoxic microenvironment in tumors, and high levels are linked to high-grade malignancies, indicating that further research on cancers associated with hypoxia is of great importance." (PMID 33708767, 2021). "In the reverse Warburg Effect model, ROS from normoxic cancer cells cause metabolic changes, including the upregulation of glycolysis-related kinases, through the elevation of HIF-1α in the surrounding CAFs48; this indicates that hypoxia can also affect glycolysis." (PMID 33994540, 2021). "Moderately increased ROS in hypoxic cancer cells could stabilize HIF-1α and mediate various tumorigenesis-associated signaling pathways, including AKT, NF-κB, AMPK and Notch 55-60." (PMID 34158854, 2021). "HIF‐1α expression is associated with cancer aggressiveness in GC." (PMID 33773069, 2021). "In addition, MB knockdown caused higher levels of HIF-1α protein after treatment with NO, which also plays an important role in cancer cell survival." (PMID 34671319, 2021). "ENO1 is a glycolysis-associated enzyme that participates in various cancers; therefore, we focused on glycolysis-associated pathways; the mTOR/HIF1α pathway is also involved in glycolysis." (PMID 33968941, 2021). "Indeed, elevated levels of HIF-1α have been found to be associated with poor patient survival rates in 19 types of cancers." (PMID 33796526, 2021). "Meanwhile, loss of HIF-1α in cancer cells was found to slow xenograft tumors." (PMID 34489398, 2021). "Thus, they promote TCA cycle and ETC functioning, and reduce ROS generation and oxidative stress, while a loss of SIRTs enhances metabolic reprogramming in cancer cells through destabilization of HIF-1α to down-regulate glycolytic genes." (PMID 32252351, 2020). "Furthermore, oxidative stress caused by cancer cells also induces autophagy by activating pro-autophagic factors like hypoxia-inducible factor 1 subunit alpha (HIF-1α) and NF-κB." (PMID 33123479, 2020). "Indeed, other reports have associated HIF-1α expression with increased mortality for several cancers, such as cervical, breast, endometrial, oropharyngeal and ovarian cancer." (PMID 33135539, 2020). "Subsequently, HIF-1α binds to the hypoxia response elements regulating the transcription of genes implicated in critical aspects of cancer biology as angiogenesis, stem cell maintenance, metabolic reprogramming, epithelial-mesenchymal transition, invasion, metastasis and resistance to therapy." (PMID 32778144, 2020). "The main effects of HIF-1α on cell physiology involve cell cycle arrest, induction of angiogenesis, and metabolic reprogramming, and these change have been associated to poor prognosis in several cancer types." (PMID 32932943, 2020). "Increased fumarate and decreased iron levels in Fh-deficient cancer cells inactivate prolyl hydroxylases, leading to stabilization of hypoxia-inducible factor (HIF)-1α and increased expression of genes such as VEGF and glucose transporter 1 (GLUT1) to provide fuel needed for rapid growth demands." (PMID 32973493, 2020). "The effect of different SNPs in HIF-1α and cancer susceptibility remain indistinct." (PMID 33154192, 2020). "Potential effect of IL-4 and IL-13 (250 ng/mL, 24 h) on the expression of genes encoding proteins relevant for cancer development by facilitating angiogenesis (HIF1A and VEGFA), inflammation (PTGS2, NOS2, CCL2), and metabolic reprogramming (GLUT1, ODC1, NOS2) was evaluated." (PMID 32512917, 2020). "This metabolic shift from TCA to glycolysis, which is a hallmark of cancer, is regulated by HIF1α." (PMID 32905943, 2020). "HIF-1α-EMT transcription factors association studies in different cancer types." (PMID 32322559, 2020). "More importantly, it is encouraging that we arrived at an important conclusion that different SNPs in HIF-1α may exhibit different effects on cancer risk." (PMID 33154192, 2020).
cancer (continued). "Similarly to PDK1, PDK3 is induced by HIF-1α, and higher expression is associated with higher tumor stage in many cancers." (PMID 33384955, 2020). "Moreover, similar to other cancers, hypoxia has been associated with induction of metastasis in OS and ES via regulation of HIF1α through HIF1α or overexpression of CXCR4 in ES, amongst others." (PMID 31963599, 2020). "Although telomerase regulation by hypoxia through the HIF-1α, the main regulator of gene transcription by hypoxia, has been described in both cancer and normal cells, the association between hypoxia and telomerase-dependent telomere maintenance has never been described in NB tumors." (PMID 32825087, 2020). "In addition, the expression of HIF-1α in cancer tissues was associated with metastasis and recurrence." (PMID 31892989, 2020). "HIF-1α is a major cellular sensor of low oxygen levels (hypoxia), the expression of which can be induced by hypoxia itself as well as by environmental conditions associated with pathological stress such as inflammation, bacterial infection or cancer." (PMID 32343720, 2020). "Notably, in LKB1-deficient cancer cell lines, the metabolic reprogramming effect is regulated by HIF-1α, which executes its antagonism by suppressing mTORC1." (PMID 32331347, 2020). "Furthermore, several phytochemicals with a known antioxidant activity can down-regulate the expression of HIF-1α, which is known to be associated in cancer with increased levels of reactive oxygen species (ROS)." (PMID 33052979, 2020). "Glufosinate treatment in vitro, as low as 10 μM, recapitulates the effect of MSO on IL10 macrophages, leading to a metabolic reprogramming, associated with a HIF1α‐dependent M1‐like phenotype, that functionally translates into a decreased immune suppression, angiogenesis, and cancer cell invasion." (PMID 32885605, 2020). "Furthermore, the expression of HIF-1α is associated with the reduction of ROS in cancer cells, which promotes cancer cell survival." (PMID 33144918, 2020). "The underlying crosstalk of lncRNA and HIF-1α in cancer progression may lead to clinical applications." (PMID 32331347, 2020). "Interestingly, a strong association of HIF1α expression by cancer cells with low iNOS+TIL score was noted, bringing forward hypoxia as a micro-environmental condition that sustains a cold immune environment." (PMID 33167430, 2020). "Binding leads to decreased expression of HIF1A, thereby reducing the risk of cancer." (PMID 31744467, 2019). "Our analysis showed that HIF-1α rs11549465 C>T polymorphism could increase risk of overall cancer risk and specific cancer risk." (PMID 31762805, 2019). "The results indicated that HIF-1α rs11549465 C>T was significantly related to the increased risk of overall cancer under four genetic models (TT vs. CC: OR=2.06, 95% CI=1.34-3.16; TT vs. CC/CT: OR=2.42, 95% CI=1.60-3.65; CT/TT vs. CC: OR=1.21, 95% CI=1.04-1.40; T vs. C: OR=1.29, 95% CI=1.12-1.48)." (PMID 31762805, 2019). "In addition to hypoxia, HIF1α-mediated transcription can be induced by circumstances associated with pathological stress including cancer, inflammatory mediators, and bacterial infection." (PMID 31440740, 2019). "High HIF-1α expression is associated with poor prognosis in many cancers." (PMID 31277295, 2019). "HIF-1α rs11549465 C>T polymorphism was previously investigated in various types of cancer." (PMID 31762805, 2019). "In addition to cancer metabolism, hypoxia signaling contributes to systemic glucose and lipid metabolism; depletion of HIF1α in pancreas β-cells causes glucose intolerance due to impaired insulin secretion." (PMID 31717493, 2019). "Moreover, androgen and Tip60 promote HIF-1α activation, shown to promote metabolic reprogramming by increasing glycolysis, a hallmark of cancer initiation and development." (PMID 31671779, 2019).
cancer (continued). "Indeed, HIF-1α has been validated as a promising target for novel cancer therapeutics, even as clinical investigations have linked increased levels of HIF-1α with aggressive cancer progression as well as poor patient prognosis." (PMID 31485300, 2019). "Thus, the relationship between HIF-1α rs11549465 C>T polymorphism and cancer risk requires further exploration." (PMID 31762805, 2019). "Taken together, these data imply that the delay and reduction of HIF-1α stabilization in CI-deficient cancer cells was caused by simultaneous increase in α-KG concentrations and reduced oxygen consumption, which together lead to a boost of PHD activity regardless of external hypoxia." (PMID 30796225, 2019). "In cancer cells, hypoxia causes genetic changes that induce expression of hypoxia-inducible factor 1α (HIF-1α), a transcription factor that binds to hypoxia-response elements involved in angiogenesis and glucose metabolism, and in cell proliferation, invasion, and metastasis." (PMID 31077234, 2019). "Moreover, androgen and Tip60 promotes HIF-1α activation, involved in metabolic reprogramming by increasing glycolysis, a hallmark in cancer initiation and development." (PMID 31671779, 2019). "Recent evidence has also implicated HIF1α with the reductive glutamine pathway in cancer." (PMID 29951485, 2018). "Importantly, the mRNA expression of a cancer-specific OATP1B3 variant is induced by the hypoxia-inducible factor (HIF-1α), which mediates cell survival under hypoxic conditions." (PMID 30131693, 2018). "Thus, elevated FKBP38 levels are associated with increased HIF-1α activity and tumor progression in glioblastoma as part of mechanisms that de-sensitize cancer cells to pro-differentiating BMP2 signals." (PMID 30314361, 2018). "As an additional aspect, we have recently reported that acidic cancer cells undergo a metabolic change characterized by the acquisition of a more OxPhos phenotype through the inhibition of HIF1α expression, associated with a reduced proliferation compared to standard pH condition." (PMID 30466459, 2018). "In addition to our metabolomics analyses, we also assessed protein levels of the hypoxia inducible factor 1 α (HIF1α), an established marker for OR and implicated in cancer." (PMID 29402948, 2018). "The overexpression of HIF-1α might sequentially lead to an increased cancer susceptibility and metastasis." (PMID 30135144, 2018). "If this is true also in man, it may cause a chronically elevated HIF-1α activity in our patients, potentially increasing their risk of developing cancer." (PMID 29321044, 2018). "Also other intracellular metabolites, such as pyruvate, lactate and oxaloacetate block PHD-mediated inhibition of HIF-1α underlying its prominent basal activity, commonly seen in many highly glycolytic cancer cells." (PMID 29434587, 2018). "Thus, the de-repression of Hif-1α we observe following mutation of p38α in HCT116 cancer cells appears to reflect an evolutionarily conserved mechanism relevant to normal physiology." (PMID 30332653, 2018). "Furthermore, the effects of PAC-1 on HIF1α stabilization and DNA damage were validated in HepG2 cells and two other cancer cell lines, and the underlying mechanism was revealed." (PMID 30287840, 2018). "It has been proposed that cancer cells possessing mutations within the PTEN gene are more resistant to cetuximab-mediated reduction of the HIF-1α level, which might be of importance in our observations." (PMID 28468237, 2017). "Melatonin reduces HIF-1α levels in several cancer cell lines, although the underlying mechanisms remain unclear." (PMID 29207653, 2017).
cancer (continued). "We found that hypoxia induces, via a HIF-1α-dependent mechanism, expression of a small set of microRNAs, miR-155, miR-193b, miR-194, and miR-210 that have also been implicated in the metabolic reprograming of cancer cells." (PMID 28099149, 2017). "High expression of HIF1α and Glut-1 are associated with poor prognosis in cancer patients." (PMID 28447025, 2017). "Here, we review and discuss the non-canonical regulation of HIF-1α expression and stabilization in cancer cells, focusing on factors which cause pseudohypoxia (HIF-1α stabilization in normoxic conditions) or fail to stabilize HIF-1α in low oxygen atmosphere (pseudonormoxia)." (PMID 29230384, 2017). "Next, we investigated the underlying mechanisms of the enhanced sensitivity of cancer cells to DDP by HIF-1α downregulation, and found a switch of the metabolic pathway from glycolysis to oxidative phosphorylation, which caused an increase in ROS and sensitized the cells to DDP." (PMID 28790395, 2017). "HIF-1α has been implicated as an oncogene that is overexpressed in some human cancer cells." (PMID 26867977, 2016). "The degree of HIF1α stabilization in cancer cells is associated with the metabolic pathways." (PMID 26885366, 2016). "Our aim was to determine whether the good prognosis of encapsulated CRLM is associated with reduced HIF-1α expression by the cancer." (PMID 26937938, 2016). "Activated PHD1, in turn, induces HIF-1α degradation, thereby causing cancer cell death in hypoxia." (PMID 27263528, 2016). "We first investigated whether docetaxel-induced cancer cell death was caused by PHD1-dependent HIF-1α degradation." (PMID 27263528, 2016). "Second, overactivation of mTOR-S6K1 pathway causes HIF-1α activation, which may lead to the migration and invasion of cancer cells." (PMID 27167192, 2016). "Indeed, HIF1a has been well studied in cancer progression and is implicated in the malignancy phenotype of LSCC." (PMID 28033431, 2016). "To examine whether the mutations of HIF-1α occurring in cancer affect its methylation status and lead to the regulation of protein stability, we performed methylation assays with SET7/9 using various HIF-1α MTs in the presence of MG132." (PMID 26757928, 2016). "Importantly, S28Y and R30Q mutations of HIF-1α, found in human cancers, are involved in the altered HIF-1α stability." (PMID 26757928, 2016). "Data suggested that high HIF-1α-levels might be associated with more aggressive cancer characteristics." (PMID 27780920, 2016). "Over-expression of HIF1α has been associated with enhanced cell migration of cancer cell." (PMID 27708247, 2016). "Therefore, it seems reasonable that increased HIF-1α levels in human cancers are positively correlated with the increased risk of mortality." (PMID 27066002, 2016). "Many studies have associated hypoxia and HIF-1α expression with cancer progression." (PMID 26869355, 2016). "HIF-1α was considered an unfavorable prognostic marker in various cancers, but the underlying mechanism of the opposing effects of HIF-1α overexpression in different subcellular compartments remains speculative." (PMID 26402839, 2015). "As a step towards understanding this complexity, we employed 8-week intermittent induction of a stable HIF-1α variant, HIF1α(PP), in various cancer cell lines and examined the effects on malignant progression in xenografts of immunocompromised mice in comparison to those of HIF2α(PP)." (PMID 25893706, 2015). "This regulatory feedback loop underlies the ability of cancer cells to maintain high HIF-1α expression in hypoxic conditions, and also explains the high endogenous levels of HIF-1α observed in PC-3 and DU-145 cells, both of which exhibit upregulated ILK expression." (PMID 25821081, 2015). "However, another kind of α-KG analogues, such as Octyl-2KG and related derivatives, significantly down-regulate HIF-1α in multiple cell types, including cancer cells with IDH1 or SDH mutations, by acting as a PHD cofactor to promote PHD function." (PMID 25420025, 2014).
cancer (continued). "Regarding the HIF-1α C1772T polymorphism, our results suggested a significant association in four genetic comparison models, providing convincing evidence that the HIF-1α C1772T polymorphism may be a risk factor in cancer development." (PMID 25496056, 2014). "In general, one could say that the cellular response to hypoxia is intended to prevent cell death and indeed an increased level of intracellular HIF-1α has been associated with a poor prognosis and resistance to therapy in cancer." (PMID 25421331, 2014). "Similarly, the statistically significant association between the HIF-1α G1790A polymorphism and cancer susceptibility was found to be consistently strong in all of the genetic models." (PMID 25496056, 2014). "Accumulation of their products, fumarate and succinate, inhibits the α-KG-dioxygenases including JmJC histone demethylases and PHDs with an associated increases in histone and DNA methylation and HIF1α accumulation, which is thought to contribute to the cancer phenotype." (PMID 24858415, 2014). "Hence, we performed a meta-analysis of all of the eligible studies to clarify the role of HIF-1α C1772T/G1790A polymorphisms in cancer development." (PMID 25496056, 2014). "FH-deficient cancer cells display pseudo-hypoxia with aberrant activation of HIF1α." (PMID 25671107, 2014). "Hypoxia-inducible factor-1α (HIF-1α) is a key transcription factor, and its overexpression is linked to a myriad of pathological consequences in many types of cancer, including breast, ovarian, renal carcinoma, glioblastoma and leiomyoma (and references therein)." (PMID 25420025, 2014). "In conclusion, this meta-analysis provides powerful evidence that both the C1772T and G1790A polymorphisms in the HIF-1α gene may contribute to individual susceptibility to cancers." (PMID 25496056, 2014). "Indeed, reduced O2 availability induces HIF-1α, which regulates the transcription of a set of genes that encode proteins involved in various aspects of cancer biology." (PMID 24400010, 2013). "Considering the similarity and overlap of functions between the two Twist proteins in development and cancer, we hypothesized that an association existed between Twist2 and HIF-1α." (PMID 23946798, 2013). "This implies that next to being involved in early BRCA mutation-related carcinogenesis, hypoxia and HIF-1α overexpression may also be a driver of cancer progression, especially in BRCA1 mutation carriers." (PMID 23409121, 2013). "We assessed the associations between the HIF-1α C1772T polymorphism and cancer metastasis." (PMID 24015181, 2013). "Stratified analysis of HIF-1a polymorphisms on cancer metastasis." (PMID 24015181, 2013). "However, the expression and regulation of HIF-1α in cancer-associated adipose stromal cells is less well characterized." (PMID 23566437, 2013). "HIF-1α 1772 C/T and 1790 G/A polymorphisms are significantly associated with higher cancer risk." (PMID 24260383, 2013). "First, estrogen and progestin can enhance the expression of HIF-1α via Akt signaling pathway which could cause cancer cell angiogenesis or invasion." (PMID 24367595, 2013). "However, studies on the association of HIF-1α 1772 C/T and 1790 G/A polymorphisms with cancer are conflicting." (PMID 24260383, 2013). "Indeed, HIF-1α stabilization in cancer cells results in decreased respiration and associated ROS production which renders these cells more resistant to apoptotic stimuli." (PMID 26316984, 2013). "In summary, this meta-analysis provided insights into the association of HIF-1α 1772 C/T and 1790 G/A gene polymorphisms with cancer risk, supporting the hypothesis that HIF-1α polymorphisms are a susceptibility marker of cancer." (PMID 24260383, 2013). "Thus, both HIF1A and its encoding gene are supposed to be promising candidates in the pathogenesis of cancers." (PMID 23723982, 2013).